GIMAP8 (GTPase, IMAP family member 8)
Description:
Exerts an anti-apoptotic effect in the immune system and is involved in responses to infections.
Synonyms: IAN-9; IAN9; IANT; DKFZp667I133; hIAN6; IAN6
Tractability: PROTAC: ubiquitination databases record sites on it; its protein half-life has been measured.
Gene: Protein-coding gene on chromosome 7 (150,450,630 to 150,479,395, forward strand). Ensembl gene ENSG00000171115.
Subcellular location: Endoplasmic reticulum; Golgi apparatus; Mitochondrion; Cytoplasm, cytosol
Gene Ontology:
Molecular function: GTPase activity; GTP binding
Cellular component: endoplasmic reticulum; Golgi apparatus; mitochondrion; cytosol
Genetic constraint (gnomAD): Loss-of-function variants: 26 observed, 32.65 expected, observed/expected ratio (o/e) 0.8, 90% interval 0.58 to 1.11. The upper end of that interval is the gene's LOEUF score, 1.11, which puts it in group 4 of 6, group 1 being the genes least tolerant of losing a copy. Missense variants: 794 observed, 829.06 expected, observed/expected ratio (o/e) 0.96, 90% interval 0.9 to 1.02. Synonymous variants: 329 observed, 321.85 expected, observed/expected ratio (o/e) 1.02, 90% interval 0.93 to 1.12.
Homologues: Orthologues: chimpanzee GIMAP8 (99% identical), macaque GIMAP8 (89% identical), rabbit GIMAP8 (66% identical), dog GIMAP8 (57% identical), pig GIMAP8 (55% identical), rat Gimap8 (54% identical), mouse Gimap8 (53% identical). Paralogues in human: GIMAP6 (14% identical), GIMAP2 (14% identical), GIMAP4 (14% identical), GIMAP5 (14% identical), GIMAP1 (13% identical), GIMAP7 (13% identical), GIMD1 (7% identical).
Diseases named in the same sentence as GIMAP8 in open-access papers:
GIMAP8 is named in the same sentence as 11 diseases in open-access papers, as found by Europe PMC text mining. Sharing a sentence is not in itself a finding about the gene and the disease. The quoted sentences say what the papers report.
breast carcinoma (3 papers, 2022 to 2025). "Another bioinformatic analysis on GIMAP family members indicated that GIMAP7 together with GIMAP1, GIMAP5, GIMAP6, and GIMAP8, are lowly expressed in breast cancer tissues." (PMID 38151913, 2024). "Bioinformatics show GIMAP1, GIMAP5, GIMAP6, GIMAP7, and GIMAP8 are downregulated in breast cancer." (PMID 40535419, 2025). "GIMAP8 is a GTP-binding with a tumor suppressive role against breast cancer." (PMID 35740301, 2022).
lung carcinoma (2 papers, 2021). "The survival analysis of the GIMAP family was performed, and the results showed that high levels of GIMAP1, GIMAP2, GIMAP4, GIMAP5, GIMAP, GIMAP7 and GIMAP8 mRNA expression levels were associated with better overall survival of patients with lung cancer." (PMID 34604035, 2021). "Abnormal expression of GIMAP family members in cancer tissues has also been reported in non-small cell lung cancer, and qPCR analysis showed downregulation of GIMAP6 and GIMAP8 in lung cancer tissues." (PMID 33691643, 2021).
endothelial dysfunction (1 paper, 2022). In vascular diseases, endothelial dysfunction is a systemic pathological state of the endothelium (the inner lining of blood vessels) and can be broadly defined as an imbalance between vasodilating and vasoconstricting substances produced by (or acting on) the endothelium. "IQCJ-SCHIP1 and GIMAP8 can be suggested as a novel genes requiring further investigation in the context of genotoxic stress induced endothelial dysfunction." (PMID 36140167, 2022).
Immunodeficiency (1 paper, 2021). Failure of the immune system to protect the body adequately from infection, due to the absence or insufficiency of some component process or substance. "A region on Chr4 included three GTPase genes (GIMAP7, GIMAP4, and GIMAP8), IMAP family members that have been related to the primary immunodeficiency pathway and were shown to play a major role in feed utilization and the metabolism of lipids, sugars, and proteins in Jersey cattle." (PMID 33633776, 2021).
lung adenocarcinoma (1 paper, 2021). A carcinoma that arises from the lung and is characterized by the presence of malignant glandular epithelial cells. "Based on BMP5 and closely related hub genes such as CHRDL1, GIMAP8, and KAL1, we constructed and improved a prognostic risk model that effectively evaluated the prognosis of lung adenocarcinoma." (PMID 34745928, 2021). "Consistently, we also found that GIMAP8, as a BMP5 co-expressed hub gene, was downregulated in tumor tissues, and its higher expression indicated better prognosis in lung adenocarcinoma." (PMID 34745928, 2021).
lymphopenia (1 paper, 2009). Reduction in the number of lymphocytes. "While we can exclude theinvolvement of the members of the Gimap family proximal to D4Rhw6 (Gimap8, Gimap9, Gimap4, Gimap6, and Gimap7)in the development of lymphopenia, we cannot exclude that they may play a rolein the development of T1D." (PMID 19421422, 2009).
tumor (4 papers, 2020 to 2022). "As early as in 2008, a study reported that GIMAP8 was significantly reduced in the lung tumor tissues and suggested a potential role in tumor immunity." (PMID 34745928, 2021). "In a study of non-small-cell lung cancer (NSCLC), it was found that GIMAP8 was abnormally expressed in tumor tissue in lower levels than in the adjacent nontumor tissue." (PMID 36199786, 2022). "Interestingly, our data show a significant decrease in mRNA levels of GIMAP4, GIMAP6, GIMAP7 and GIMAP8 in BC tissues, compared to DCIS tissues, and non-tumor breast tissues from either women with or without BC (supplementary 2)." (PMID 32523132, 2020).
infection (2 papers, 2006 to 2022). The state of being infected such as from the introduction of a foreign agent such as serum, vaccine, antigenic substance or organism. "GIMAP proteins are thought to be involved in the control of cell survival and response to infection and GIMAP8 has been shown to have anti-apoptotic functions." (PMID 16515715, 2006).
GIMAP8 also shares sentences with these, for which no sentence is quoted: cancer (1 paper); coronary heart disease (1); non-small cell lung carcinoma (1).